MYBL1 (MYB proto-oncogene like 1)
Diseases named in the same sentence as MYBL1 in open-access papers (continued):
Sharing a sentence is not in itself a finding about the gene and the disease.
tumor (continued). "In adenoid cystic carcinoma (ACC), tumor-promoting fusion proteins of MYB and MYBL1 with nuclear factor IB (NFIB) were identified." (PMID 38835346, 2024). "Our findings highlight the importance of the MYBL1 gene in HCC development and emphasize the need for diverse approaches in evaluating tumor mechanisms." (PMID 39408891, 2024). "The different expression in tumor cells from different organ systems further complicates the understanding of the role of NTF-3 and MYBL1 in tumorigenesis." (PMID 39408891, 2024). "These neoplasms are frequently categorized based on specific genetic changes such as FGFR1, MYB/MYBL1, BRAF, or IDH1/2, identified through DNA methylation profiles." (PMID 38137148, 2023). "We firstly found that expression of MYBL1 was higher in HCC tissues, compared with para-tumor tissues." (PMID 35987690, 2022). "Although recent study has demonstrated that MYBL1 promotes growth and metastasis of HCC cells via upregulated TWIST1 expression, however, the clinical significance and molecular mechanisms of MYBL1 underlying tumor angiogenesis in HCC remain remains largely unknown." (PMID 35987690, 2022). "Gene fusions involving MYB, MYBL1, and NFIB, which were found in nearly 90% of our SAdCC cases, are currently considered to be the primary oncogenetic event in SAdCC, and RAS mutations may confer progressive or invasive features on the tumor cells, resulting in a worse prognosis for SAdCC patients." (PMID 29682203, 2018). "Strategies focused on down-regulating TMEM158, Mybl1, IL32, ETS1 and PTX3 should be considered to determine their effect on TNBC tumor progression." (PMID 28966727, 2017). "Interestingly, when we evaluated the possible correlation between NTF-3 and MYBL1 gene expression in tissue samples from patients with HCC of viral origin, cirrhotic tissue, and non-tumor liver tissue, we found a positive correlation only in the HCC group." (PMID 39408891, 2024). "Probes that specifically target the unique MYBL1 exon show that the exon is overexpressed in tumor cell lines compared to non-tumor breast cells." (PMID 39796135, 2024). "Previously, upregulated MYBL1 expression was found in HCC tissue compared to the liver tissue adjacent to the tumor, even though it did not have significantly changed expression according to several bioinformatical analyses." (PMID 39408891, 2024). "In previous studies, we were able to use optimized RNA-seq approaches to successfully analyze the transcriptomes of archived, formalin-fixed, paraffin-embedded ACC tumor samples up to 25 years old, which led to the identification of the first ACC tumors with MYBL1 translocations." (PMID 36900183, 2023). "Furthermore, this tumor type is characterized by recurrent molecular alterations, especially rearrangements involving the MYB, MYBL1, and NFIB genes." (PMID 37476370, 2023). "Here we propose that NK-like cells expressed the transcription factors KLF2, KLF3, and MYBL1, which have been also reported as features of cytotoxic, non-dysfunctional subsets in tumours infiltrating T cells." (PMID 38012187, 2023). "Taken together, our study provides new knowledge about the prevalence and clinical significance of MYB and MYBL1 alterations in ACC and indicates the presence of genes with tumor suppressive functions in 6q23.3-qter that contribute to poor prognosis in a subset of tumors." (PMID 35954356, 2022). "MYBL1 rearrangements and translocations were not present in any tumor sample analyzed." (PMID 39199639, 2024). "Furthermore, the in vivo results showed that silencing ANGPT2 significantly reduced the fluorescence intensity in MYBL1-overexpression tumor cells and downregulation of ANGPT2 dramatically reduced the number of CD31-positive microvessels in MYBL1 transfected mice." (PMID 35987690, 2022).
tumor (continued). "Interestingly, ACC tumor samples with mutations in NOTCH1 and SPEN had no alterations in MYB and MYBL1, suggesting that other genetic events than alterations in MYB/MYBL1 may also play a central role in developing the ACC." (PMID 37476370, 2023).
cancer (30 papers, 2011 to 2025). A tumor composed of atypical neoplastic, often pleomorphic cells that invade other tissues. "The MYBL1 gene is a strong transcriptional activator involved in events associated with cancer progression." (PMID 38473786, 2024). "CERS6, TCF7, and MYBL1 stood out as common regulators in at least four networks, all three TFs have been implicated in the cancer process." (PMID 26606983, 2015). "We found that a 4-hour treatment with the pan-HDACs or HDAC4 inhibitor in MIA PaCa-2 and BxPC3 cancer cells decreased the protein levels of MybL1." (PMID 41281751, 2025). "MYB and MYBL1 regulate the expression of cell cycle protein-dependent kinases, which contribute to cancer development." (PMID 38877400, 2024). "Because MYBL1 is a strong transcription factor known to be involved in (and likely affect) events related to the pathogenesis of cancer, we are devoting studies to better understanding the gene in TNBC." (PMID 38473786, 2024). "The human family of MYB transcription factors comprises MYB (c-MYB), MYBL2 (b-MYB), and MYBL1 (a-MYB), which are overexpressed in several cancers and are associated with cancer progression and resistance to anticancer drugs." (PMID 38835346, 2024). "IHC showed that MYBL1 was overexpressed in ccRCC cancer tissue compared with the normal tissue obtained from four patients." (PMID 36591240, 2022). "Together these data support the association of MYBL1, IL32, TMEM158 and ETS1 with certain TNBCs and the enrichment of genes involved in immune related processes as differentially associated with the cancers." (PMID 28966727, 2017). "Several cancer-promoting genes were uperegulated (Ctgf, H19, Mmp12, Mybl1, Vnn1) while cancer inhibiting genes (Cish, Dkk4, Onecut1, Scara5, Socs3, Wif1) were suppressed." (PMID 26200659, 2015). "For example, three members of the TF family MYB: MYB, MYBL1 and MYBL2, appear to be closely associated with cancer." (PMID 22041030, 2011). "Because the cancers often express immune signatures, we performed unsupervised meta-analyses of GEO TNBC microarray datasets and then further subdivided the cancers based on immune signatures, which subsequently led to the identification of MYBL1 differential expression." (PMID 38473786, 2024). "Aside from structural alterations that lead to changes in the gene’s performance, transient changes in events associated with the carboxyl terminus might contribute to effects on MYBL1 gene expression in cancers." (PMID 38473786, 2024). "In HCC, MYBL1 is shown to promote cancer cell proliferation by activating TWIST1 transcription." (PMID 35681031, 2022). "In the future, more basic studies focused on MYBL1 in cancers, especially in ccRCC, are needed." (PMID 36591240, 2022). "Therefore, our results uncover a novel mechanism for upregulation of ANGPT2 in cancer and indicate an oncogenic role for MYBL1 in HCC angiogenesis and sorafenib resistance." (PMID 35987690, 2022). "However, a significantly higher level of MYBL1 was noticed in patients with worse M- and N-stage, indicating its promoting effect in cancer metastasis." (PMID 36591240, 2022). "Previous studies have identified MYBL1 as a cancer-promoting molecule in numerous types of cancer." (PMID 36591240, 2022). "Moreover, regardless of ER status, cancers with high HSF1 levels revealed a higher expression of MYBL1 than cancers with low HSF1 levels." (PMID 34783649, 2021). "Interestingly, this analysis revealed that the MYB mRNA level was strongly reduced in the basal cancer subtype, and those of MYBL1 and MYBL2 increased, compared to the levels in normal tissue, partially in line with our finding that p95HER2 expression shifts the miRNA profile towards this subtype." (PMID 30833639, 2019). "Inhibition of HDAC4 reduces migration of cancer cells and decreases the mRNA and protein levels of transcription factor MYB Proto-Oncogene Like 1 (MybL1) and YAP." (PMID 41281751, 2025).
cancer (continued). "The fact that MYBL1 is over-expressed in TNBC and is a strong transcription factor that drives the expression of other genes implicates the gene in cancer processes." (PMID 38473786, 2024). "Myb and Mybl1 transcription factors belong to MYB gene family, which has been well-defined in controlling cell survival, proliferation, and differentiation in cancer (Cicirò and Sala, 2021)." (PMID 38536963, 2024). "MYBL1, MME and LRMP, as key regulators of the cell cycle, have been identified as potential therapeutic targets for cancer." (PMID 28423735, 2017). "Importantly, we found that both the pan-HDAC inhibitor Saha and the HDAC4 specific inhibitor Lmk-235 significantly decreased the mRNA level of the transcription factor MybL1 in MIA PaCa-2 and PANC-1 cancer cells." (PMID 41281751, 2025).
CNS tumors (3 papers, 2022 to 2024). "Overall, further investigation of the various types of MYB/MYBL1 alterations and their role in CNS tumor development is needed to precisely characterize these tumors and their clinical behavior." (PMID 39422766, 2024).
gastrointestinal tumors (1 paper, 2022). "It would be worthy to further investigate whether MYBL1 plays a role in promoting angiogenesis and metastasis in others gastrointestinal tumors." (PMID 35987690, 2022). "More importantly, we found that the clinical relevance of MYBL1 and ANGPT2 was further confirmed in multiple gastrointestinal tumors." (PMID 35987690, 2022).
head and neck tumor (1 paper, 2025). "Our findings expand the molecular landscape of rare MYB or MYBL1 fusion-negative AdCC patients and provide a potential therapeutic strategy for this rare head and neck tumor." (PMID 40184085, 2025).
immune dysfunction (1 paper, 2022). "It seems that MYBL1 had no significant influence on the TIDE score, immune exclusion, immune dysfunction quantified by the TIDE analysis." (PMID 36591240, 2022).
infection (1 paper, 2024). The state of being infected such as from the introduction of a foreign agent such as serum, vaccine, antigenic substance or organism. "After infection with Lenti-MYBL1, the activity of HUVECs was enhanced, and their migration ability was stronger than that of the control cells." (PMID 38797732, 2024).
MYBL1 also shares sentences with these, for which no sentence is quoted: anaplastic astrocytoma (3 papers); ganglioglioma (3); glioblastoma (3); mucoepidermoid carcinoma (3); glioneuronal tumors (2); myoepithelioma (2); pilocytic astrocytoma (2); acute kidney injury (1); adenoid cystic carcinomas of the breast (1); asthma (1); autoimmune encephalitis (1); Azoospermia (1); brain tumor (1); cerebral tumor (1); chronic lymphocytic leukemia (1); chronic lymphoid leukemia (1); cutaneous adenocystic carcinoma (1); cylindroma (1); cyst (1); embryonal tumor (1); epilepsy (1); esophageal carcinoma (1); follicular lymphoma (1); gastric cancer (1); hemorrhage (1); hidradenocarcinoma (1); hidradenoma (1); high-grade glioma (1); invasive ductal breast carcinoma (1); invasive lobular breast carcinoma (1).
A further 23 diseases each share a sentence with MYBL1 in 1 paper.